PINK1 (PTEN induced kinase 1)
Diseases named in the same sentence as PINK1 in open-access papers (continued):
Sharing a sentence is not in itself a finding about the gene and the disease.
ischemic stroke (10 papers, 2021 to 2025). A stroke disorder caused by obstruction of blood flow to the brain, due to thrombotic (local blood clot formation) or embolic (due to a blood clot or other material traveling from another site) event. "During mitochondrial dysfunction caused by ischemic stroke, the PINK1/Parkin pathway mediates the polyubiquitin of the functional or structural proteins in the damaged mitochondria." (PMID 34335233, 2021). "However, TSG could promote the transfer of Parkin to mitochondria, which led to the downregulation of Tomm20 in mitochondria, indicating activation of PINK1/Parkin-mediated mitophagy might be implicated in the neuroprotection of TSG on ischemic stroke." (PMID 39406480, 2024). "Ligustilide activates adenosine 5‘-monophosphate (AMP)-activated protein kinase (AMPK) signaling and PTEN induced putative kinase 1 (PINK1)/Parkin expression, which helps alleviate ischemic stroke damage." (PMID 40235541, 2025). "Collectively, TSG facilitated PINK1/Parkin pathway-mediated mitophagy by upregulating USP10/YBX1 axis to ameliorate ischemic stroke." (PMID 39406480, 2024). "Mechanically, TSG upregulated USP10 to elevate YBX1 protein expression, thereby facilitating PINK1/Parkin-mediated mitophagy and improving ischemic stroke injury." (PMID 39406480, 2024). "DHA alleviates neuronal injury and motor dysfunction after ischaemic stroke by clearing damaged mitochondria via Pink1/Parkin-mediated mitophagy." (PMID 36254232, 2022). "Upon ischemic stroke, the mitochondria membrane is depolarized, which prevents the import of PINK1 and results in the accumulation of PINK1 on the mitochondrial membrane." (PMID 34168551, 2021). "We explored whether TSG improved ischemic stroke injury via PTEN-induced kinase 1 (PINK1)/Parkin-mediated mitophagy." (PMID 39406480, 2024). "We hypothesized that TSG upregulated USP10 to improve brain injury in ischemic stroke via promoting PINK1/Parkin-mediated mitophagy." (PMID 39406480, 2024). "Thus, PINK1/Parkin-mediated mitophagy is an important therapeutic target against ischemic stroke." (PMID 39406480, 2024). "Safarpour’s studies on ischemic stroke using neurons found that knockout of PINK1 or Parkin gene could result in excitatory amino acid toxicity to the neurons, and it was confirmed that either PINK1 or Parkin gene deletion could aggravate neuronal damage in ischemic stroke." (PMID 34335233, 2021). "Through animal experiments of intracerebral hemorrhage, ischemic stroke, SAH and traumatic brain injury, PINK1 is well acknowledged as a protective factor against extensive forms of acute and chronic brain injuries." (PMID 40979207, 2025). "This study indicates that LIG can improve neuron damage in ischemic stroke by promoting mitochondrial autophagy through PINK1/Parkin, and targeting PINK1/Parkin-mediated mitochondrial autophagy and LIG therapy may be a promising therapeutic strategy for ischemic stroke." (PMID 38650626, 2024).
lung adenocarcinoma (10 papers, 2020 to 2025). A carcinoma that arises from the lung and is characterized by the presence of malignant glandular epithelial cells. "Survival analysis revealed that PI3K and PINK1 expression levels in primary lung adenocarcinomas were significantly associated with OS when patients were stratified according to specific cutoff points." (PMID 40243539, 2025). "Altogether, these findings suggest that PI3K and PINK1 alterations are associated with carcinogenesis, particularly in lung adenocarcinomas with BM, potentially due to their roles in mitophagy, metabolic reprogramming, and modulation of the tumor microenvironment." (PMID 40243539, 2025). "In addition, our findings indicate a possible association between PI3K/PINK1 expression and survival in this subgroup of lung adenocarcinoma with resected brain metastases, though further studies are required to confirm their prognostic value and underlying mechanisms." (PMID 40243539, 2025). "Taken together, these results require validation in prospective studies that also include lung adenocarcinomas with metastases to other anatomical sites, further supporting the clinical utility of PINK1 and PI3K immunoexpression for prognostic assessment." (PMID 40243539, 2025). "Kaplan–Meier survival analysis was performed to evaluate the prognostic impact of PI3K PINK1 and PD-L1 expression on OS in lung adenocarcinoma patients with BM." (PMID 40243539, 2025). "For example, mitophagy mediated by PINK1 in lung adenocarcinoma cells and tissues can promote oxidative phosphorylation and redox homeostasis, leading to the development of sustained drug resistance in tumor cells and resulting in poor prognosis." (PMID 41138746, 2025). "In this study, we aimed to investigate PI3K and PINK1 immunoexpression in lung adenocarcinomas with resected brain metastases and assess their potential prognostic significance." (PMID 40243539, 2025). "In accordance with our data, a recent discovery indicates that PINK1-dependent mitophagy is required for inducing and maintaining a drug-tolerant state in lung adenocarcinoma." (PMID 38514650, 2024). "Expression of PINK1 is reported to be essential in maintaining high mitochondrial activity described in drug-tolerant persistent lung adenocarcinoma cells, with PINK1 ablation resulting in decrease in OxPhos." (PMID 39440945, 2024). "Elevated PINK1 expression is significantly correlated with postoperative chemoresistance in lung adenocarcinoma." (PMID 38155968, 2023). "Studies have demonstrated a significant correlation between high PINK1 expression and postoperative chemoresistance in lung adenocarcinoma." (PMID 38155968, 2023). "Studies have shown a significant correlation between elevated PINK1 expression and postoperative chemoresistance in lung adenocarcinoma." (PMID 38155968, 2023). "In this work, we studied the immunohistochemical expression of the kinases PI3K, PINK1, and PD-L1 in a specific subset of patients with lung adenocarcinomas—only those who underwent surgical resection of their BM—to better describe molecular alterations at this stage of advanced disease." (PMID 40243539, 2025). "In lung adenocarcinoma cells and organoids, PINK1 has been found to be upregulated to sustain mitochondrial homeostasis during DTP generation, and PINK1-induced mitophagy drives DTP production upon MAPK inhibition." (PMID 39035027, 2024). "The E3 ubiquitin-ligase ARIH1 and not Parkin mediates PINK1-induced mitophagic responses to cisplatin/etoposide in breast and lung adenocarcinomas." (PMID 33280610, 2020). "From a translational perspective, therapies targeting these pathways, such as PI3K inhibitors or mitophagy modulators like metformin, may hold promise for improving patient outcomes, particularly in those with lung adenocarcinoma and BM exhibiting high PI3K and PINK1 expression." (PMID 40243539, 2025).
lung adenocarcinoma (continued). "In addition, PRKN, PINK1 and MAP1LC3A, expression levels were positively correlated with the infiltration score, as well as the infiltration of various immune cells, including iTreg, effector memory, exhausted, Th1, and nTreg cells in lung adenocarcinoma (LUAD)." (PMID 39859167, 2025).
atherosclerosis (9 papers, 2020 to 2023). A disease characterized by the build-up of fatty material and calcium deposition in the arterial wall resulting in partial or complete occlusion of the arterial lumen. "Increased inflammation in atherosclerosis may be caused by increased PINK1 cleavage in mitochondria and impaired mitophagy." (PMID 35525979, 2022). "Such as, in ApoE−/− mice induced atherosclerosis, apelin-13 enhanced Pink1/Parkin-mediated mitophagy via activating p-AMPKα, therefore, induced VSMC proliferation to aggravate the development of atherosclerotic lesions." (PMID 36353377, 2022). "The atherosclerosis feeding protocol used littermate and sex-matched controls and the Pink1 transgenic group fed up to 16 weeks of age." (PMID 34576157, 2021). "Nevertheless, these results, and the calculation of a vulnerability index, do suggest that Pink1 protects against atherosclerosis." (PMID 34576157, 2021). "In AS, apelin-13 increases mitophagy by activating the PINK1/Parkin pathway, and F13A is an apelin-13 antagonist in PINK1 and Parkin-dependent mitophagy, which blocks the effect of apelin-13 in the progression of atherosclerosis." (PMID 32257551, 2020). "Silencing of PINK1 and Parkin reduced mitophagy in atherosclerosis and enhanced apoptosis in VSMCs via ox-LDL." (PMID 32257551, 2020). "We targeted Pink1 as it plays a central role in mitochondrial homeostasis but may also be important in the emerging role of mitochondrial dysfunction in atherosclerosis." (PMID 34576157, 2021). "However, after a 10 week high-fat diet feeding regime to induce atherosclerosis, Pink1-KO mice had significant changes to the quality of plaque composition." (PMID 34576157, 2021). "Comparing wild-type VSMCs from an ApoE model of atherosclerosis with a flox’d Pink1 knockout of inducible mitochondrial dysfunction we show WT Pink1 is essential for normal cell viability, while Klotho mediates energetic switching which may preserve cell survival." (PMID 35008643, 2021). "In addition, in the absence of a secreted protein known to participate in atherosclerosis, apolipoprotein A-I binding protein (AIBP), PINK1 is cleaved, and mitophagy is blocked, which also promotes atherosclerosis progression and plaque formation." (PMID 38020895, 2023).
esophageal squamous cell carcinoma (9 papers, 2020 to 2025). Esophageal squamous cell carcinoma (ESCC) is a type of esophageal carcinoma (EC) that can affect any part of the esophagus, but is usually located in the upper or middle third. "This discovery might challenge a previous report stating that high expression of PINK1 is a poor prognostic factor for patients with esophageal squamous cell carcinoma treated with neoadjuvant chemotherapy." (PMID 33244455, 2020). "PINK1 was upregulated in esophageal squamous cell carcinoma (ESCC) tissues from patients who received chemotherapy." (PMID 34568319, 2021). "It has been reported that PINK1 and LC3 are significantly upregulated in patients with esophageal squamous cell carcinoma, and inhibition of mitophagy can restore chemosensitivity in these patients." (PMID 41429797, 2025). "In esophageal squamous cell carcinoma (ESCC) patients, PINK1-mediated mitophagy promotes tumor cell survival under neoadjuvant therapy." (PMID 35851420, 2022). "It is also reported that PINK1 and LC3 were significantly upregulated in the esophageal squamous cell carcinoma patients, and inhibition of mitophagy restored the chemosensitivity in those patients." (PMID 33446239, 2021). "However, the relationship between PINK1 and PARK2 and esophageal squamous cell carcinoma (ESCC) remains unknown." (PMID 37833780, 2023).
myeloma (9 papers, 2018 to 2025). "The PINK1 gene encodes a mitochondrial serine/threonine protein kinase, and previous studies in MM cells have shown that PINK1-dependent mitophagy plays a key role in regulating myeloma migration, homing, and tumorigenesis." (PMID 39726602, 2024). "To further confirm the role of the PINK1-PARK2 pathway in the ABC294640-mediated mitophagy, we knocked down PINK1 or PARK2 using specific shRNA in myeloma cell lines." (PMID 36975444, 2023). "We then analyzed the correlation between level of PINK1‐dependent mitophagy and overall survival in myeloma patients." (PMID 32154065, 2020). "The effects of PTEN‐induced putative kinase 1 (PINK1)‐dependent mitophagy on the pathogenesis of multiple myeloma (MM) are determined." (PMID 32154065, 2020). "In summary, we have unequivocally shown that PINK1‐dependent mitophagy plays a critical role in regulating myeloma cell migration, spreading, and tumorigenesis." (PMID 32154065, 2020). "Using MOB1B‐specific shRNA knockdown and YAP/TAZ genetic overexpression, we have further demonstrated an important role of MOB1B‐YAP/TAZ pathway in PINK1‐mitophagy‐mediated myeloma cell migration." (PMID 32154065, 2020). "To determine if salinomycin induced mitophagy in our in vivo myeloma xenograft model, we measured PINK1 expression in splenocytes." (PMID 32154065, 2020). "Compared to cell proliferation and apoptosis, the effect of PINK1 overexpression on myeloma cell migration was more profound, suggesting that PINK1‐dependent mitophagy predominantly affects myeloma cell migration." (PMID 32154065, 2020). "This study uses genetic and pharmacologic approaches to provide direct evidence that PINK1‐dependent mitophagy plays a critical role in regulating myeloma migration, homing, and tumorigenesis." (PMID 32154065, 2020). "Furthermore, the stimulation of PINK1-dependent mitophagy with salinomycin or carbonylcyanide-m-chlorophenylhydrazone or an augmented expression of PINK1 provokes a reduction in myeloma cell homing and reduced osteolytic bone lesions." (PMID 33924049, 2021). "Our study demonstrates that PINK1‐dependent mitophagy can be targeted for the treatment of myeloma." (PMID 32154065, 2020). "We next set out to determine how PINK1‐dependent mitophagy contributes to myeloma pathogenesis." (PMID 32154065, 2020). "However, MOB1B‐specific shRNA knockdown restored at least in part myeloma cell transwell migration that was attenuated by PINK1 overexpression." (PMID 32154065, 2020). "We have also shown that the level of PINK1‐dependent mitophagy correlates with myeloma patient's clinical outcomes and that noninvasive cfPINK1 level could be a useful marker for in vivo mitophagy measurement." (PMID 32154065, 2020). "Overexpression of YAP or TAZ abrogated the effects of PINK1 on myeloma cell migration." (PMID 32154065, 2020). "Furthermore, we found that PINK1 overexpression had minimal effects on myeloma cell cycling or on the induction of apoptosis." (PMID 32154065, 2020). "In the present study, PIWIL1 was found to modulate autophagy-related proteins LC3, p62, and mTOR and the canonical PINK1/PARKIN pathway proteins, indicating that PIWIL1 promoted myeloma growth by modulating autophagy/mitophagy." (PMID 35083142, 2021). "Similar to PINK1 overexpression, treatment with CCCP or salinomycin significantly reduced myeloma cell migration in vitro." (PMID 32154065, 2020). "Collectively, these findings suggest that UNC13B may regulate multiple oncogenic and apoptotic signaling pathways—such as those involving PINK1, CDK2, AKR7A3, and Bim—to promote cell survival and proliferation in multiple myeloma." (PMID 41007649, 2025). "The levels of the PINK1‐dependent mitophagy markers PINK1 and parkin RBR E3 ubiquitin protein ligase (PARK2) in CD138+ plasma cells are reduced in patients with MM and correlate with clinical outcomes in myeloma patients." (PMID 32154065, 2020).
myeloma (continued). "To further confirm whether MOB1B has a direct role in PINK1‐mediated myeloma cell migration, we knocked down MOB1B using MOB1B‐specific shRNA in the PINK1 overexpression MM cells and examined its effects on the expression of YAP and TAZ and myeloma cell transwell migration." (PMID 32154065, 2020). "Moreover, the induction of PINK1‐dependent mitophagy with carbonylcyanide‐m‐chlorophenylhydrazone (CCCP) or salinomycin, or overexpression of PINK1 leads to inhibition of transwell migration, suppression of myeloma cell homing to calvarium, and decreased osteolytic bone lesions." (PMID 32154065, 2020). "This inhibitory effect on myeloma cell proliferation seen with CCCP and salinomycin but not with PINK1 gene overexpression is likely related to the dramatic and rapid burst of mitophagy induction with the pharmacological approach." (PMID 32154065, 2020). "Unlike PINK1 genetic overexpression, treatment with CCCP or salinomycin significantly inhibited myeloma cell survival and proliferation." (PMID 32154065, 2020).
myocardial ischemia (9 papers, 2020 to 2025). A disorder of cardiac function caused by insufficient blood flow to the muscle tissue of the heart. "Further, the effect of PINK1-deficient cardiac ischemia/reperfusion injury on myocardial injury is exacerbated further than in the wild-type, and overexpression of PINK1 in HL-1 cardiac cells protects cardiomyocytes from hypoxia/reoxygenation injury." (PMID 36132224, 2022). "In myocardial ischemia/reperfusion injury, inhibiting PINK1/Parkin-mediated mitophagy could reduce ROS production and protect against neurons damage." (PMID 33424757, 2020). "And in myocardial ischemia/reperfusion injury, activation of PINK1/Parkin-mediated mitophagy could reduce cell apoptosis and inflammatory response." (PMID 33424757, 2020). "First, Sal B can further induce NLRP3 inactivation by inhibiting intracellular ROS production during myocardial ischemia, increasing the mitochondrial membrane potential, regulating the expression levels of SIRT1, Parkin, and PINK1 proteins, and promoting mitochondrial autophagy." (PMID 39323645, 2024).